CCND1 (cyclin D1)
Diseases named in the same sentence as CCND1 in open-access papers (continued):
Sharing a sentence is not in itself a finding about the gene and the disease.
tumor (continued). "The ultimate expression of the downstream targets cyclin D1, cyclin D2 and COX-2 were also significantly downregulated in the Anthos group for both adjacent normal (P = 0.0009, P = 0.001, and P = 0.0009, respectively) and tumor tissue samples (P = 0.0004, P = 0.03, and P = 0.03, respectively)." (PMID 34926717, 2021). "Moreover, to further confirm the effect of DHX32/β-catenin pathway on HCC proliferation and EMT in vivo, we should also detect the expression of proliferation makers, such as PCNA, Cyclin D1, β-catenin expression, and EMT markers including E-cadherin and vimentin in the tumour tissues." (PMID 33729094, 2021). "Additionally, overexpression of Cyclin D1, a binding partner with CDK4/6, in neuroblasts and low Cyclin D1 expression in ganglioneuroma indicate an involvement of dysregulation of the G1 cell cycle checkpoint in neuroblastic tumor differentiation." (PMID 34069817, 2021). "Hence, a combination of inhibitors blocking both pathways could lead to a significant tumor growth reduction together with a decrease in proliferation indexes, including RB1 phosphorylation, E2F1, CCND1, and PCNA expression levels, in the NPC PDX model." (PMID 34204797, 2021). "At days 7, 17, and 24, mice implanted with tumor at day 0 were vaccinated with anti-CD40 11B6-CD40L-Doc, anti-CD40 11B6-Doc, IgG4-CD40L-Doc, and non-targeting IgG4-Doc non-covalently linked to human Coh-Cyclin D1." (PMID 35095862, 2021). "Importantly, similar to short-term Olaparib treatment, RT-PCR analysis of parental and Olaparib-resistant A2780, OVCAR8, and PEO1 cells showed mRNA upregulation of several essential tumor-promoting genes, such as MMP9, VEGFA, CCND1, and BCL2L1, which are known STAT3 target genes." (PMID 34956861, 2021). "Low‐dose HBBR could interfere with the expression of cyclin‐D1 and E1 to induce G1 cycle arrest and induce caspase pathway to increase apoptosis, and may inhibit the PI3 K/Akt pathway in A549 cells, thus significantly inhibiting tumor growth." (PMID 33650320, 2021). "To assess the relationship between CCND1 amplification and the landscape of immune cell infiltration, we used an algorithm called ESTIMATE to analyze the infiltrating fraction of stromal and immune cells in tumor samples from the TCGA pan-cancer cohort (n = 2,633)." (PMID 32903763, 2020). "Indeed, cyclin D1 and cyclin B protein levels were markedly reduced in GEM-implanted tumor lysates." (PMID 32111094, 2020). "Compared to the control, the protein expression levels of STAT3, p-STAT3Ser727, p-STAT3Tyr705, Bcl2, cyclin D1, and c-myc were lower in the Stattic and CTS-treated groups, indicating that STAT3 might be important for tumor development and progression in TA2 SBC." (PMID 32432040, 2020). "Consequently, the expression of GM-CSF, TSLP, phosphorylated STAT3, β-catenin, and cyclin D1 in the transplanted tumors was evaluated using Western blotting, and the expression of GM-CSF, TSLP, β-catenin and cyclin D1 was examined in tumor sections." (PMID 32887217, 2020). "Furthermore, CCND1 and EGFR show an additive effect on OSCC tumor progression." (PMID 33317149, 2020). "Although EHD can regulate the STAT3/cyclin D1 pathway and delay the growth of LC, it could not completely inhibit the growth of xenograft tumours." (PMID 32382281, 2020). "Still, it was frequently expressed and may have a role in tumor suppression, contrasting with Cyclin D1 that did not seem to present a pivotal role as reported in GCA." (PMID 32466539, 2020). "Protein expression of genes CCND1 and c-myc which are downstream of CTNNB1 in the WNT-pathway could be demonstrated as well, but protein expression was relatively weak as expected for a benign tumor." (PMID 32155193, 2020). "In addition, these specific anti-tumor actions of Calebin A further correlated with inhibition of cell metastatic (CXCR4, MMP-9) and proliferative (cyclin D1) biomarkers, all of which are known to have a NF-κB binding site in their promoters, thus promoting their transcription." (PMID 32708030, 2020).
tumor (continued). "In this tumor, negative modulation of the CDX2/miR-615-5p/IGF2 axis was associated with increased tumor size and weight in animal models, as well as increased expression of tumor progression markers such as Ki-67, cyclin D1, c-MYC and Bcl-2." (PMID 32605009, 2020). "Moreover, there was a weak correlation between the expression of CCND1 and FGA (r = 0.238), but not tumor mutation counts (data not shown)." (PMID 33299117, 2020). "However, no statistical significance was found in the comparison of CCND1 expression with the T stage of tumor (GSE21034 P = 0.148Figure 1(c)) or Gleason score (GSE21034 P = 0.257Figure 1(d))." (PMID 32566661, 2020). "Notably, CCND1 and CDKN2A alterations were only found in the HPV-negative tumor samples." (PMID 30934880, 2019). "This hypothesis is supported by patient data from the PAMOLA-1 study showing no benefit of palbociclib in patients whose tumours were CCND1-amplified." (PMID 30819233, 2019). "This may partially explain why luminal A CCND1-amplified tumours demonstrate poorer survival relative to their non-amplified counterparts." (PMID 30819233, 2019). "However, the low level of CCND1, but not high level of CCND1, was related to poor prognosis and tumor recurrence in ccRCC." (PMID 31183974, 2019). "Therefore, we hypothesised that the suppression of tumour growth of GC by RN181 may undergo by reducing the expression and assembly of cyclin D1 with CDK4 mediated by inhibition of ERK/MAPK signalling in the stomach." (PMID 30714150, 2019). "Examining the same genes in CCND1-amplified vs. non-amplified luminal A tumours showed increased MKI67 and decreased PGR gene expression in amplified tumours (see “MKI67” and “PGR”, P < 0.001 and P = 0.002 respectively), consistent with a more aggressive phenotype." (PMID 30819233, 2019). "Similarly, drugs did not impact on mTOR S2448, VEGFR2 Y996, pERK T202/Y204 and Cyclin D1 expression levels in tumor counterparts while Tensirolimus reduced cancer organoid capacity formation." (PMID 30814510, 2019). "Moreover, by analysing the GSE37364 datasets, we found that cyclin D1, CDK4, and Twist1 were significantly up-regulated in CRC tissues, whereas E-cadherin was significantly down-regulated in CRC tissues when compared with the non-tumour tissues (all p < 0.05)." (PMID 31772673, 2019). "Out of 134 core disks, 10 (7.46%) cores could not be analysed for cyclin D1: 8 (5.97%) contained no tumour cells, 1 (0.75%) was lost during processing, and 1 (0.75%) had not sufficient cells for scoring resulting the elimination of 2 (2.99%) cases." (PMID 29785357, 2018). "In cultured RCC cells, knockdown of G3BP1 results in inhibition of tumor cell proliferation, migration, and invasion, consistently with the alteration of epithelial–mesenchymal transition (EMT) and cell proliferative markers, including Cadherins, Vimentin, Snail, Slug, c-Myc, and cyclin D1." (PMID 29717134, 2018). "Out of 134 core disks, 14 (10.4%) could not be evaluated for CCND1 analysis: 8 (5.97%) contained no tumour cells and 6 (4.5%) were lost during processing." (PMID 29785357, 2018). "Furthermore, cell cycle-related proteins, including cyclin D1, CDKs, ORC6 and MCMs, were downregulated in the xenograft tumour tissues after treatment with T-96 compared with controls, and these trends were largely consistent with the previous experimental results." (PMID 30305611, 2018). "Expression of Cyclin D1 was significantly higher in OIII (median expression 45% versus 14% for OII, p = 0.0006) and was correlated with MIB-1 expression (p<0.0001), vascular proliferation (p = 0.002), tumor necrosis (p = 0.04) and a shorter EFS in the total cohort (p = 0.05)." (PMID 29489901, 2018).
tumor (continued). "Consistent with our theory, the protein expression of MMP7 and CCND1 were downregulated in a SOX30-overexpressing cell line and xenograft tumors; MMP7 and CCND1 expression were increased significantly in SOX30-overexpressing cells, or tumor tissue after DSP or JUP expression was blocked." (PMID 29855376, 2018). "Interestingly, SMARCA4 (also known as BRG1) is a transcriptional regulator that can control the activity of Sonic hedgehog and GliA and their downstream targets, providing a driving force for tumor proliferation by activating mitogenic genes such as GLI1, CCND1 and MYC." (PMID 29137349, 2017). "Indeed, the application of SB431542 reduced cyclin D1-expressing liver CSC spherogenesis and sphere-derived tumor growth, although the inhibition efficacy was limited with no xenograft tumor could be eradicated." (PMID 28415588, 2017). "Given the critical role of MCM7 in DNA replication licensing and causing chromosome instability, and the strong association between MCM7 and cyclin D1 expression in both human HCC tissue and murine xenograft tumor, it is reasonable to hypothesize that MCM7 acts as a regulator of cyclin D1." (PMID 28182015, 2017). "Furthermore, in an immunohistochemistry assay, we observed that the expression levels of RTL1, c-MYC, CYCLIN D1 and β-CATENIN in tumour tissues were increased after overexpression of RTL1 and decreased with RTL1 knockdown, in agreement with previous findings in A375 cells." (PMID 29285312, 2017). "CSCs are characterized by their tumor forming ability and expression of high levels of ATP-binding cassette drug transporters (ABCG2), cell adhesion molecules (CD44), and anchorage independent cell survival proteins (Cyclin D1), which are collectively responsible for chemo-resistance." (PMID 28536422, 2017). "Thus, miR-503 functions as a tumor suppressor and has an important role in ESCC by targeting CCND1." (PMID 28602785, 2017). "Mechanistically, cyclin D1 could transcriptionally down-regulate NTCP expression, which might attribute to the decreased expression of NTCP in hepatocytes with rapid cell cycle progression including HCC tumor cells." (PMID 28915572, 2017). "Il6 deficiency also reduced hepatic mRNA levels of Stat3 target genes (Birc5, Bcl2l1 and Ccnd1), cyclins (Ccna2, Ccnb1, Ccnb2), and markers of proliferation (Mki67) and HCC (Afp) in livers from FGF19-expressing mice, further demonstrating the role of IL-6 in mediating FGF19-driven tumour growth." (PMID 28508871, 2017). "Thus, Smad inhibitors can drive cyclin D1-Smad-mediated CSC into a more differentiated state that is sensitive to chemotherapy at the cellular level and minimizes tumorigenicity at the in vivo xenograft tumor level." (PMID 28415588, 2017). "Additionally, the overexpression of CCND1 is known to be present in many neoplasms, malignant, and non-malignant, and it is considered one of the most important tumorigenic factors." (PMID 28382019, 2017). "Examination of two markers of cell proliferation, Cyclin D1 and Ki-67, revealed the presence of more advanced (uniformly Cyclin D1-positive) tumors in the MYO1E WT PyMT mice and a higher proportion of cells positive for Ki-67 in the MYO1E WT PyMT tumors and tumor cell cultures." (PMID 27329840, 2016). "Our findings of CCND1 and/or CDK4 allow us the suggestion that the selective CDK4/6 inhibitor Palbociclib (IBRANCE®, Pfizer Inc.)may be a promising treatment option in unresectable or metastasized tumor stages." (PMID 26943575, 2016). "Results from our ChIP-Seq analysis identified oncogenic c-Myc, Cyclin D1, Ets2, Akt1 and Notch2, pro-inflammatory Hsp90, pro-lymphangiogenic VEGF-C, and pro-apoptotic p27 as novel transcriptional targets of MTA1, revealing its ability to simultaneously activate multiple tumor-promoting pathways." (PMID 26943043, 2016). "Also increased was oncogene cyclin D1 and EMT markers, which promoted tumor progression." (PMID 26909607, 2016).
tumor (continued). "Cyclin D1 (CCND1) promotes the G1/S-phase transition, and its expression changes during malignant transformation in the MMTV-PyMT model, suggesting that it could serve as a useful marker of tumor progression." (PMID 27329840, 2016). "Besides, we also found that miR-146a-5p could inhibit tumor growth in xengroft mouse models, and CCND1 and CCND2 were downregulated in miR-146a-5p overexpressed xengroft tumor tissues." (PMID 27494902, 2016). "Paired paraffin embedded pre- and post-statin treatment tumor samples were analyzed using immunohistochemistry for the expression of estrogen receptor (ER), progesterone receptor (PR), human epidermal growth factor receptor 2 (HER2), and the cell cycle regulators cyclin D1 and p27." (PMID 25925673, 2015). "STAT3 activity supports tumour-cell survival by up regulating expression of the anti-apoptotic protein BCL-XL (B-cell lymphoma-2-like) and many other proteins involved in cell proliferation and survival including myeloid cell leukaemia 1 (MCL1), cyclin D1 and MYCC." (PMID 26186918, 2015). "Speculatively, augmentation of cyclin D1 might trigger a negative feedback loop, cancelling the blockade of tumour cells in reaching late G1 restriction." (PMID 25808196, 2015). "Alteration of the miR-15a and miR-16-1 translates into multiple tumor-promoting processes through the derepression of key cell cycle-and apoptosis-related genes such as B-cell CLL/lymphoma 2 (BCL2), wingless-type MMTV integration site family-member 3A (WNT3A) and cyclin D1 (CCND1)." (PMID 25309903, 2014). "Furthermore, the expression of cyclin D1 gradually increased in the NOT, OSA, OS-BT and OSC groups and was associated with tumor metastasis." (PMID 24348821, 2014). "Furthermore, we examined protein levels of β-catenin and cyclin D1 in 56 ESCC tumor and corresponding non-tumor tissues." (PMID 25160749, 2014). "In order to understand how PFEC induced apoptosis of tumor cells and inhibited cell proliferation, we detected gene expression of cell growth and anti- and pro-apoptosis genes such as Akt, PI3K, Bcl-2, Bcl-xL, Bax, Bid and cell proliferation gene cyclin D1 and PCNA in cells by quantitative PCR." (PMID 25029345, 2014). "Therefore, it is possible that the water decoction of Taxus cuspidate which may inhibit expression of these cyclin D1 and CDK4 to suppress the tumor growth." (PMID 24719642, 2014). "However, the inverse correlation of cyclin D1 and YAP1 protein expression observed in the randomised tumour material remained after removing the CCND1 amplified cases from the analysis, indicating additional functions for maintaining the negative relationship between the two proteins." (PMID 24559095, 2014). "Also in these tumor cells, PI3K inhibition dose dependently reduced β-Catenin transcriptional activity and readily reduced the expression of the WNT target genes c-MYC, Cyclin-D1 and notably LEF-1." (PMID 24930890, 2014). "Thus, interruption of cyclin D1-mediated cell cycle progression does not appear to be responsible for the inhibitory effects of Se-casein on tumor growth observed in the current study." (PMID 24152862, 2013). "Several studies support the notion that the oncogenic effects of cyclin D1 may not be simply due to enhanced tumor cell growth or proliferation." (PMID 23786849, 2013). "As depletion of p21 alone did not affect tumor formation in a Xenograft transplantation in vivo model, it is likely that the observed phenotype on tumor formation in the double knockdown is mediated by cyclin D1." (PMID 23786849, 2013).
tumor (continued). "Our results indicate that there might be other HRGs that mediate the critical oncogenic activity of HIF in RCC, as VEGF or Cyclin D1 overexpression failed to drive efficient tumor growth in VHL+/+ cells as the overexpression of HIF2α did." (PMID 24260413, 2013). "A likely mechanism for this tumor-specific effect is that BA inhibited DUB activity specifically in PC but not in normal cells, resulting in increased poly-Ub proteins and enhanced degradation of proliferation and pro-survival proteins such as cyclin D1 and AR by the UPS." (PMID 23424652, 2013). "Thus it seems that although both VEGF and Cyclin D1 were able to promote tumor growth, neither of which was as powerful as HIF." (PMID 24260413, 2013). "Many studies have been done on cyclin D1 in OSCC, and even though the controversy exists in the scientific literature, it opens a window of opportunity for further discussion and research in different tumours with additional different criteria like lymph node involvement and metastasis." (PMID 22629227, 2012). "Dhar and colleagues reported that expression of CCND1 was up-regulated in about 90% of patients with EOC and expressed mainly in both borderline and invasive tumours without any association between immunoreactive protein overexpression and stage of tumor differentiation or grade of tumor." (PMID 23236518, 2012). "Furthermore, we could show the cyclin D1 overexpression on mRNA and protein level, consolidating the diagnosis of a MCL-like neoplasia." (PMID 21457541, 2011). "Earlier studies conductedon several neoplasias suggest that cyclin E may mimic cyclin D1 byhyper-phosphorylating pRb in the absence of cyclin D1." (PMID 21455311, 2011). "Even though resistant tumor cells can escape immune recognition from γδ T cells by down regulating surface expression of MICA, γδ T cells can still be able to slow down the progression of the tumor cell proliferation by inhibiting cell cycle related molecules CDK2, CDK4 and Cyclin D1." (PMID 21935360, 2011). "But we showed higher cyclin D1 expression in galectin-3 negative tumor tissues." (PMID 22024187, 2011). "As a possible reason for these differences of cyclin D1 overexpression, although early differentiated-type cancers, except for gastric phenotype, do not require an increase of cyclin D1, once the tumor has developed, the tumor cells need a high level of cyclin D1 for tumor progression." (PMID 20525401, 2010). "We previously reported that down-modulating cyclin D1 and inhibiting cyclin dependent kinases (cdks) using either flavopiridol or a combination of N-(4-hydroxyphenyl)retinamide (4-HPR) with 4OH-Tam is effective in inhibiting RTs in vitro and in xenograft tumor models in vivo." (PMID 21092078, 2010). "Finally, Cyclin D1 expression did not correlate with the important prognostic indicators like tumor size and mitotic rate." (PMID 18651966, 2008). "However, it should be noted that a number of cyclin D1-positive tumours in all three localisation groups had a low proliferative index, demonstrating that cyclin D1 expression itself is not sufficient to induce cellular proliferation." (PMID 17375037, 2007). "However, in this case it was found that cyclin D1 was up-regulated in the mammary lesions of the caveolin-1 null mice as compared to the normal tumour prone mice, but no change in the activation state of the p42/44 MAPK cascade was observed." (PMID 18949068, 2007). "In addition, our data indicate that in HC11 cells PI-3-kinase regulated the EGF-dependent transcription of cyclin D1 and osteopontin (OPN) (Wang, Galbaugh, and Cutler, unpublished observation), both of which are regulated by the PI-3-kinase pathway in tumor cells." (PMID 16984645, 2006). "The apparent phase-restricted expression of cyclin D1 suggests that previous observations of its expression throughout the cell cycle in tumour cell lines may not be reflected in vivo." (PMID 16832409, 2006).